BCL2 (BCL2 apoptosis regulator)
Diseases named in the same sentence as BCL2 in open-access papers (continued):
Sharing a sentence is not in itself a finding about the gene and the disease.
ischemic stroke (56 papers, 2009 to 2025). A stroke disorder caused by obstruction of blood flow to the brain, due to thrombotic (local blood clot formation) or embolic (due to a blood clot or other material traveling from another site) event. "For instance, hsa-miR-143-3p—which affects neutrophil counts mediated by BCL2 expression—has been implicated in numerous immunological diseases such as cancers and ischemic stroke, has been found to influence inflammatory factors and cell apoptosis, and to inhibit Wnt and MAPK signaling." (PMID 37303042, 2023). "To determine whether the NXC736-mediated neuroprotective effects were associated with the attenuation of apoptosis in ischemic stroke, we examined Bcl-2, an apoptosis-regulating protein, and cleaved-caspase-3, a key marker of apoptosis, using Western blot analysis." (PMID 41375102, 2025). "Conversely, anti-apoptotic molecules such as Bcl-2 and Bcl-XL are essential for supporting neuronal viability and reducing infarct size in both transient reperfusion and permanent ischemic stroke models." (PMID 41373489, 2025). "The neuroprotective mechanisms are associated with regulations of TLR4/NF-κB/NLRP3/ caspase-1 and caspase-3 signals, as well as Bcl-2/Bax ratio, suggesting SO is a novel neuroinflammatory regulator in ischemic stroke." (PMID 40289983, 2025). "After ischemic stroke, pathological brain damage is aggravated by increased apoptosis, which manifests as a sharp increase in caspase-3 and a slight upregulation of Bcl-2 levels." (PMID 38500994, 2024). "The study found that electroacupuncture treatment can significantly reduce ischemic stroke-induced caspase-3 and the up-regulation of caspase-3, thereby reversing the down-regulation of the b-lymphoma-2 gene (Bcl-2) and reducing apoptosis." (PMID 38721046, 2024). "Hou, etc. ’s study showed that mTOR phosphorylation was reduced, along with Bcl-2 expression in the animal model of ischemic stroke." (PMID 38015410, 2024). "Previous studies have shown that 24 h after ischemic stroke, both apoptotic caspase-3 and anti-apoptotic Bcl-2 are simultaneously overexpressed in the ischemic area." (PMID 38500994, 2024). "The mitochondrial apoptotic pathway plays an essential role in neuronal injury, and TAT-PEP inhibited neuronal apoptosis after ischemic stroke by upregulating Bcl-2 expression and reducing Bax expression." (PMID 37335462, 2023). "Activation of Bcl-2 was investigated in a few models of ischemic stroke, and the results varied depending on the brain area investigated and the intensity of the ischemic process." (PMID 37204689, 2023). "Collectively, these results provide mechanistic evidence that the ERK1/2/CREB/BCL2 signaling pathway plays a role in the neuroprotective effect of artemisinin on ischemic stroke." (PMID 35864966, 2022). "Mechanistically, YTHDC1 promoted PTEN mRNA degradation to increase AKT phosphorylation, thus up-regulating the expression of Bcl-2, down-regulating the expression of cleaved caspase-3 and facilitating neuronal survival after ischemic stroke." (PMID 36246528, 2022). "The results showed that artemisinin significantly protected neuronal cells and brain tissues from ischemic stroke via the ERK1/2/CREB/BCL-2 signaling pathway." (PMID 35864966, 2022). "Further, Atad1 phenocopies Bcl2 and Bcl2l1 in the middle cerebral artery occlusion mouse model of ischemic stroke: deletion of Atad1 or Bcl2 exacerbates, and overexpression of Atad1, Bcl2, or Bcl2l1 decreases ischemic cell death." (PMID 36409067, 2022). "miRNAs are thought to play an important role in ischemic stroke pathology by altering the expression, such as miR-15a, which is involved in ischemic brain injury by inhibiting the anti-apoptotic gene BCL-2." (PMID 33790947, 2021). "Delayed recanalization after middle cerebral artery occlusion ameliorated ischemic stroke by inhibiting apoptosis via the HGF/c-Met/STAT3/Bcl-2 pathway in rats." (PMID 34421795, 2021).
ischemic stroke (continued). "MiR-497 also targets Bcl-2, and antagomir miR-497 treatment increases Bcl-2 levels, which is accompanied by reduction in infarction volume during ischemic stroke." (PMID 32937836, 2020). "Our results show that the active compounds from DB closely relate to PI3K, Bcl-2, COX-2, p38, CREB, GSK3β, and TrkB, most of which were associated with oxidative stress and brain inflammation cause of ischemic stroke." (PMID 32508949, 2020). "It was suggested that the anti-apoptotic protection effects of RSAE treatment on ischemic stroke resulted from upregulating Bcl-2 protein expression and downregulating Bax protein expression." (PMID 30235876, 2018). "YQFM prevented sequestration of antiapoptotic proteins Bcl-xl and Bcl-2, and activation of proapoptotic proteins Bax and Bak induced by ischemic stroke, suggesting its protection against mitochondrial apoptosis." (PMID 29435096, 2017). "Studies have shown that TPPU can reduce the production of reactive oxygen species (ROS) after ischemic stroke, increase the expression of Bcl-2 protein, and decrease the expression of Bax protein, implying that TPPU can inhibit cell apoptosis after ischemic stroke." (PMID 36846137, 2023). "Bcl-2 is one of the anti-apoptotic genes, and lentiviral transfected Bcl-2 expressing human NSCs reportedly has better survival in the brain and improves functional recovery after ischemic stroke in acute phase transplantation." (PMID 36671605, 2022). "Furthermore, it was shown that rTMS ameliorates cognitive deficits, lesion size via the activation of Bcl-2, and inhibition of Bax and cytochrome-c release and inflammation after ischemic stroke post-hemi-cerebellectomy in rats." (PMID 35055089, 2022). "Findings regarding the effect of ischemic stroke on Bcl-2 expression are controversial." (PMID 32273547, 2020). "Explosive evidence corroborated that a sudden insult of ischemic stroke may break the balance between the anti-apoptotic and pro-apoptotic members of B-cell lymphoma-2 (Bcl-2) family, which may aggravate stroke condition." (PMID 32269527, 2020). "Results from in vitro model of ischemic stroke in rats have shown that increased Bax/Bcl-2 ratio in ischemic insult could irritate MPTP opening, which may cause increased neuronal apoptosis." (PMID 32269527, 2020). "It is speculated that overexpression of SOD3 affects the expression of Bax and Bcl‐2, and improves apoptosis to alleviate ischemic stroke." (PMID 31461803, 2019). "Considering the results of the present study, we assume that an increased expression of Bcl2 may protect brain tissue from damage due to ischemic stroke." (PMID 25722793, 2015). "Bcl2 is a protooncogene that codifies an antiapoptotic protein, which has been described as participating in neuroprotective mechanisms in ischaemic stroke although changes in the expression are limited to an increase in the neurons within the peri-infarct region." (PMID 19531214, 2009). "In conclusion, we showed that artemisinin has protective effects on PC12 cells, primary cultured neurons and an MCAO animal model, and demonstrated that artemisinin could attenuate ischemic stroke induced apoptosis through activation of the ERK1/2/CREB/BCL-2 signaling pathway in vitro and in vivo." (PMID 35864966, 2022). "Thus, we speculate that reduced apoptosis and autophagy following ischemic stroke in ethanol groups may be related to an increased Bcl-2." (PMID 32273547, 2020).
ischemic stroke (continued). "In the present study, we observed reduced expression of cleaved caspase-3 and increased expression of Bcl2 following pretreatment with H89, supporting the conclusion that H89 protects against hypoxia injury, specifically, that it increases neuronal cell survival rate after ischemic stroke." (PMID 26448879, 2015). "In ischemic stroke, Bcl-2 phosphorylation or peroxisome proliferator-activated receptor gamma (PPAR-γ) activation can disrupt or modulate the Bcl-2–Beclin1 interaction, thereby influencing autophagy induction and progression." (PMID 40943626, 2025). "We showed that ischemic stroke accompanies apoptosis and MCAO rats subjected to CM3 exert downregulation of Bax and upregulation of Bcl2 in the hippocampus." (PMID 35715988, 2022). "In this study, artemisinin reversed the ischemic stroke-induced decrease in the phosphorylation of ERK and CREB and increase in the ratio of BAX/BCL2." (PMID 35864966, 2022). "Vitexin also upregulated Bcl-2/Bax and Caspase-3 expression in OGD-treated cells, which has been identified as a key mediator of apoptosis in ischemic stroke pups." (PMID 28424420, 2017). "In ischemic stroke, mitophagy could be predominantly mediated by the PINK1/Parkin pathway, Bcl-2/E1B-19 KD-interacting protein 3 (BNIP3), NIP3-like protein X (NIX, also known as BNIP3L), and FUN14 domain containing 1 (FUNDC1)." (PMID 37033646, 2023). "In addition, the injection of IL-17A-neutralizing mAb could significantly increase Bcl-2 expression levels (p = 0.0414, n = 6 per group), but decrease the expression levels of Bax (p < 0.01, n = 6 per group) in the peri-infarct region of mice with ischemic stroke." (PMID 33101005, 2020). "Accordingly, the results in our study indicated that TEAS had the ability to enhance the levels of Bcl-2 and suppress the expression of Bax when compared to MCAO/R group, suggesting that TEAS was able to exert inhibitory effect on neuronal cell apoptosis in ischemic stroke." (PMID 38273974, 2023). "Hence, the concurrent enhancement of Bcl-2 and suppression of proapoptotic factors such as caspase-3 and BAX may be contributing to the decrease of neuronal cell death following ischemic stroke." (PMID 33664650, 2021). "In addition, miR-124 suppresses apoptosis in ischemic stroke via directly targeting and upregulating Bcl2, Bcl-xl, Usp14, JAK/STAT3, and PI3K/AKT/Nrf2 signaling pathways, while other researchers reported that miR-124 promotes neuronal apoptosis through inhibiting iASPP and Ku70 in ischemic stroke." (PMID 31878035, 2019). "EA with 5–20 Hz for 30 min once daily at Baihui (DU20) and Shenting (DU24) may enhance Bcl-2 at both protein and mRNA level, phosphorylated-CREB at the protein level, and the activity of glutathione peroxidase and superoxide dismutase in the hippocampus of rats after ischemic stroke." (PMID 30618558, 2018).
colitis (53 papers, 2012 to 2026). Inflammation of the colon. "In an in vivo colitis-associated dysplasia and tumor mouse model, Bcl-2 expression was downregulated after treatment with AntiGan." (PMID 35054489, 2022). "In a different study, the Bax/Bcl-2 ratio was higher in mice with colitis-associated cancer." (PMID 40534879, 2025). "In addition, taurine reduced the expression of Bax and prevented the loss of Bcl-2 proteins in colonic mucosa of rats with TNBS-induced colitis." (PMID 33803551, 2021). "UV‐C inactivated Lacticaseibacillus casei 39 paraprobiotic suppressed inflammation (↓TNF‐α, IL‐6; ↑IL‐10), oxidative stress (↓TOC, ↑TAC) and apoptosis (↓Bax/Bcl‐2, ↓Caspase‐3/9, ↓cyt c) in an acetic acid‐induced colitis model." (PMID 40688608, 2025). "We revealed that the ratio of Bax/BCL-2 and A-caspase-3 levels were significantly elevated in the untreated colitis group compared to the CTRL group." (PMID 39359253, 2024). "In DSS-induced colitis, elevated pro-apoptotic protein Bax and reduced anti-apoptotic component Bcl-2 were seen in acute inflammatory areas." (PMID 37646040, 2023). "Na2SeO3 regulates the IDO1/kynurenine, TLR4, NF- κB, and Bcl2/Bax pathways and attenuates acetic acid-induced colitis in rats." (PMID 39280958, 2022). "The TNBS-induced colitis rats showed a decreased expression level of Bcl-2, increased expression levels of Bax and cleaved caspase-3, and a decreased Bcl-2/Bax ratio." (PMID 35766160, 2022). "Compared with the sham group mice, the colitis model mice displayed a lower level of the colonic anti-apoptotic marker Bcl2." (PMID 34594215, 2021). "Treatment with the combination of polynucleotides and hyaluronic acid also affected Bcl-2 expression in experimental colitis, reducing apoptotic and necrotic cells in all tissue layers." (PMID 33092298, 2020). "When BER was administered, noteworthy declines (p < 0.05) were observed in caspase-3 and Bax levels with augmentation (p < 0.05) in Bcl-2 level compared to experimental colitis group." (PMID 33061833, 2020). "In comparison with the control group, notable increases (p < 0.05) in colonic proapoptosis proteins (caspase-3 and Bax) accompanied by marked decline (p < 0.05) in antiapoptotic protein (Bcl-2) were detected in rats with experimental colitis." (PMID 33061833, 2020). "Herein, we observed that BER reversed the apoptotic changes induced in experimental colitis by lessening the production of caspase-3 and Bax as well as elevating Bcl-2 level in colon mucosa." (PMID 33061833, 2020). "Cell death was suggested to be a driver of colitis and overexpression of the pro-survival protein Bcl-2 in intestinal epithelial cells ameliorated chronic inflammation in an interleukin-10 (IL-10) knockout mouse model." (PMID 31877961, 2019). "The apoptosis-related protein Bax was significantly increased and Bcl-2 was significantly decreased in colitis rats, and these changes were also reversed by PFB." (PMID 29176974, 2017). "Aloperine regulates the expression and location of PP2A and T-cell apoptosis in colitis through increased Bax expression and decreased Bcl-2 and cleaved caspase-3 expression." (PMID 29056830, 2017). "PDRN treatment also affected Bax and Bcl-2 expression in experimental colitis reducing apoptotic and necrotic cells in all tissue layers." (PMID 27601997, 2016). "Using the TNBS model, mesalamine treatment reduced colitis severity in mice in part through reducing BCL-2 colonic expression levels, which is in agreement with our finding using the DSS model where E121 also reduced its expression in the colon homogenate." (PMID 27997590, 2016). "This point was in accord with our previous study showing that SSW heightened expression of Bcl-2 mRNA in colonic mucosa from rats with colitis." (PMID 26273312, 2015).
colitis (continued). "In the present study, western blot analysis caspase-3, Bax, and Bcl-2 proteins expressions in colon tissues of AA-induced colitis animals shown a significant increase in protein expression of pro-apoptotic Bax and caspase-3 and suppression of antiapoptotic protein within the intestinal crypts." (PMID 35807383, 2022). "The low expression of Bcl2 in colitis was significantly increased by arbutin." (PMID 34594215, 2021). "The RT-qPCR results showed that ghrelin reduced the mRNA expression of GPR78, CHOP, and BAX and increased the mRNA expression of Bcl-2 in a dose-dependent manner in mice colitis models, and such an effect of ghrelin could be reversed by [D-lys3]-GHRP-6." (PMID 33776781, 2021). "The increased number of apoptotic epithelial cells and elevated Bax but attenuated Bcl-2 during active colitis may lead to a defective epithelial barrier and result in pathogenic microorganism infiltration." (PMID 33461587, 2021). "Interestingly, in recently published study it was shown that administration of Bcl-2 inhibitor was leading to amelioration of inflammation in experimental model of colitis in mice which deserves attention in searching new therapeutic options." (PMID 30515402, 2018). "The UC group showed severe colitis, increased TNF‐α and IL‐6, decreased IL‐10, elevated TOC, reduced TAC, altered VEGF/EGF mRNA, PI3K/AKT activation, and increased apoptosis (Bax/Bcl‐2 ratio, Cytochrome c, Caspase‐9, Caspase‐3)." (PMID 40688608, 2025). "At the same time, STAT3 knockout also reduced the differences in the expression of IL-6, TNF-α, and IL-1β, as well as ZO-1, occludin, BCL-2, and BAX in the colons of mice with colitis induced by different diets." (PMID 38233383, 2024). "The mRNA level of Bcl-2 was slightly increased, and the anti-apoptosis genes Bax, caspase-9, and caspase-3 largely decreased in SM934-treated colitis mice." (PMID 36120344, 2022). "In spite of this, SM934 regulated the balanced Bcl-2 and BAX, and cleaved caspase-9 and cleaved caspase-3 in colitis, and also downregulated the cleaved caspase-3 in TNF-α-induced IEC apoptosis in vitro." (PMID 36120344, 2022). "OXY treatment decreased Bax expression while upregulating Bcl-2 relative to the model group, thus decreasing the Bax/Bcl-2 ratio in rats with DSS-induced colitis." (PMID 33946346, 2021). "The down-regulation of anti-apoptotic Bcl-2 and up-regulation of pre-apoptotic Bax were observed during DSS-induced colitis." (PMID 29538417, 2018). "Because the ratio of Bax/Bcl-2, a parameter of apoptotic cell death, was increased in colon tissue of TNBS treated rats, it appears that apoptosis was involved in TNBS-induced colitis." (PMID 23209735, 2012). "In addition, CP alleviated colitis symptoms by blocking the activation of PI3K/AKT pathway in TNBS induced colitis in rats through the protein levels of AKT, BCL2, PI3K, and JNK2." (PMID 38803438, 2024). "In addition, although we attempted to study ICI-colitis CD8+ TRM cells ex vivo, the high rates of apoptosis, in keeping with down-regulated Bcl-2 expression, made this challenging." (PMID 34147519, 2021). "According to our data, Hyp upregulates the expression of Bcl-2 and downregulates the expression of the pro-apoptotic protein Bax and Caspase-3, indicating that Hyp mitigates colonic apoptosis in the mouse model of DSS-induced colitis." (PMID 29162986, 2017).
colitis (continued). "However, after experimental colitis was treated with SSP for 7 days, the protein expression of Bax and caspase-3 in colon tissue of experimental colitis mice was significantly downregulated, while the protein expression of Bcl-2 was upregulated." (PMID 35388299, 2022). "In mouse colitis models, we found that ghrelin exhibited protective effects on colitis in a GHS-R1a-dependent manner, and the effects may be mediated by the UPR components, such as caspase-3, BAX, and Bcl-2, in intestine tissues." (PMID 33776781, 2021). "Furthermore, arbutin could significantly reverse the changes of the anti-apoptotic marker Bcl2 and tight junction barrier dysfunction marker MLCK in colitis mice." (PMID 34594215, 2021).